ATG5 (autophagy related 5)
Diseases named in the same sentence as ATG5 in open-access papers (continued):
Sharing a sentence is not in itself a finding about the gene and the disease.
tumor (353 papers, 2010 to 2026). "Despite impaired CD4+ T cell activation, Atg5 deficiency in activated CD4+ T cells led to an enhanced anti-tumor response." (PMID 40977681, 2025). "The early loss of Atg5-dependent autophagy significantly accelerated tumour initiation, resulting in an increased number of tumour foci and a more rapid progression from hyperplasia to benign adenomas." (PMID 40978098, 2025). "Although no significant eQTL results were identified for this variant, the potential role of ATG5 in tumor metabolism and immune escape warrants further investigation." (PMID 38664626, 2024). "Our data showed the tumor regression under Atg5 overexpression accompanied with autophagy deficiency." (PMID 38826147, 2024). "A recent pan-cancer study using multiple public databases showed that the expression of ATG5 is associated with tumor immune infiltration in most solid tumors." (PMID 38664626, 2024). "Specific partial autophagic protein deletion (Ambra1+/−, ATG4c−/−, Sh3glb1−/− and mosaic ATG5−/−) in other mouse models was strongly associated with increased tumor incidence." (PMID 38482052, 2024). "Taken together, our data imply that overexpression of Atg5 under autophagy‐deficient conditions transiently induced tumor formation followed by tumor regression in vivo." (PMID 38826147, 2024). "Combined knock down of CD95 with that of Beclin1 or ATG5 caused a significant further reduction in tumor cell killing." (PMID 38329728, 2024). "Autophagy can also modulate tumour suppression through the induction of apoptosis operated by Atg5 and its association with proapoptotic proteins." (PMID 37174088, 2023). "Human PDAC samples have also been studied, showing that lower ATG5 levels were associated with tumor metastasis and lower survival." (PMID 35740481, 2022). "In the Atg5 knockout model, the loss of autophagy reduces tumor burden and progression to adenocarcinoma in the lung." (PMID 35689420, 2022). "In CRC, patients with high ATG5 expression generally have a poorer prognosis and are more likely to cause tumor recurrence." (PMID 36172152, 2022). "Results showed that miR-199a-5p was negatively associated with LC3II/LC3I, ATG5, and p62 and positively correlated with the tumor weight." (PMID 35292022, 2022). "On the one hand, mice with allelic loss of Beclin1 are tumor prone and liver-specific deletion of ATG5 or ATG7 induces benign hepatomas, which suggest a role for autophagy in tumor suppression." (PMID 35600411, 2022). "For instance, in pancreatic ductal adenocarcinoma, loss of ATG5 increases tumor initiation but avoids invasive cancer progression." (PMID 33937039, 2021). "Further, the expression level of ATG5 was confirmed to be associated with tumor immune infiltration and tumor microenvironment, especially in BRCA, KIRC, and LIHC." (PMID 33842365, 2021). "We have shown that loss of autophagy through ATG5 inhibits tumor growth in a cell-autonomous fashion in inflammation-driven (AOM/DSS), sporadic (Apc), and patient-derived in vitro models of CRC." (PMID 34138755, 2021). "Tumor cells isolated from Neu2-plasmid-injected human OC xenograft mice also showed the increased association of Neu2 with Atg5 leading to its desialylation, enhanced autophagosomes, and increased cell death, ultimately leading to a reduction in tumor size." (PMID 33526785, 2021). "By contrast, single-allele knockout of Atg5 led to increased malignant tumour formation and metastatic dissemination compared with mice with wild-type Atg5." (PMID 32929194, 2021).
tumor (continued). "These tumor cells showed an enhanced association of Neu2 with Atg5 that leads to increased autophagosomes and apoptotic cells." (PMID 33526785, 2021). "Autophagy-related gene 5 (ATG5) acts as a tumor suppressor protein and its absence causes tumor generation in different tissues, including breast." (PMID 33643916, 2020). "Although the autophagy modulation needs to be investigated in each case, these data indicated that tumor-specific loss of Atg5 favored Treg TILs." (PMID 33335860, 2020). "Simultaneous loss of p62 or Nrf2 in mice with livers deficient in Atg7 or Atg5 suppresses tumor development 91, 94, implying that the p62‐mediated activation of Nrf2 contributes to tumor growth in autophagy‐deficient mouse livers." (PMID 30499183, 2019). "Human PDAC samples were also monitored and lower levels of Atg5 were associated with tumor metastasis and shorter survival time." (PMID 31905604, 2019). "An increased generation of effector interferon (IFN) ɣ and TNFα-producing CD8+ T cells was observed in tumor-infiltrating lymphocytes in bone marrow chimeras bearing ATG5-deficient donor cells, which led to improved tumor control." (PMID 31632966, 2019). "Treg cells-specific deletion of Atg7 or Atg5, two essential genes in autophagy, leads to loss of Treg cells, further tumor resistance, and inflammatory disorders." (PMID 30678689, 2019). "With high expression of a hypoxia, serial autophagy markers, such as BNIP3, LC3B and ATG5, were found modulated by HIF1α, and these were often associated with aggressive tumor progression phenotype in vivo." (PMID 31700698, 2019). "Results from previous researches showed that altered ATG5 expression and/or selective allelic loss of ATG5 are associated with malignancy development, treatment resistance, and tumor progression." (PMID 29382381, 2018). "Loss-of-function in autophagy signaling mediators such as Beclin 1, Atg5, and Atg7 is strongly associated with tumor initiation and progression." (PMID 28895911, 2017). "Mice deficient in Atg5 exhibit increased expressions of cleaved Caspase 3 in colon tumors and reduced tumor size." (PMID 28977986, 2017). "NDP52 or FIP200 deletion also phenocopied ATG5 loss in elevation of TGFβ-target gene transcript levels and inhibition of tumour growth in vivo." (PMID 29146913, 2017). "We found that mice with selective Atg5 deficiency in CD4 T cells featured reduced tumour growth over controls." (PMID 28916785, 2017). "Using these cell lines or an alternate pair of wild-type and ATG5-deleted clones, we observed that loss of ATG5 markedly diminished tumour growth kinetics in vivo." (PMID 29146913, 2017). "In mice possessing an oncogenic allele of Kras, ablation of Atg5 and Atg7 prevented further tumor development." (PMID 28725634, 2017). "This notion was further supported by our observation that Spred2-mediated tumor cell death was impaired by either mutations in the LIR motifs in Spred2 or knockdown of ATG5, LC3 or p62." (PMID 27028858, 2016). "Immunohistochemistry showed positive staining of p62 in tumor cells both in Ctr mice and Atg5-deficient mice, and p62 accumulation was especially elevated in Atg5-deficient tumors, suggesting successful reduction of autophagic activity." (PMID 26496833, 2015). "The expression of CHOP was also strongly up-regulated in tumor cell nuclei of Atg5-deficient mice, according to immunohistochemical staining." (PMID 26496833, 2015). "Intratumoural injection of ARL67156 into ATG5-deficient (ATG5KD) tumour cells significantly enhanced lymphocyte recruitment into irradiated ATG5KD CT26 cancers, commensurate with the improved growth-inhibitory action of irradiation on such tumours." (PMID 24037090, 2014). "In this study, we investigated whether ATG5-mediated autophagy regulation contributes to CAR-T cell functional durability under tumor-associated stress conditions." (PMID 42099602, 2026).
tumor (continued). "Collectively, these findings demonstrate that reinforcing inducible autophagy capacity through ATG5 promotes the maintenance of CAR-T cell function under tumor-associated challenges, highlighting a targeted strategy to enhance CAR-T cell persistence in solid tumor immunotherapy." (PMID 42099602, 2026). "For example, studies using a genetically engineered mouse model with conditional deletion of Atg5 or Atg7 resulted in significant suppression of tumor growth, indicating the tumor-promoting role of autophagy, which was associated with impaired glucose homeostasis in lung tumors." (PMID 40214497, 2025). "However, loss of Atg5-dependent autophagy impaired malignant progression, as tumours showed reduced proliferation, increased apoptosis and necrosis, impaired mitochondrial function, and elevated DNA damage responses." (PMID 40978098, 2025). "Atg5 deficiency in MC38 tumor cells almost completely abolished the therapeutic effect of CV-1." (PMID 38982116, 2024). "Interestingly, a heterozygous loss of the Atg5 gene results in further tumor progression and drug resistance response." (PMID 38826147, 2024). "Altogether, the Wnt5a/JNK/β‐catenin signaling pathway activated by overexpressing Atg5 under autophagy‐deficient conditions may contribute to increased cell proliferation, migration, and tumor formation in vitro or in vivo." (PMID 38826147, 2024). "Furthermore, recent evidence revealed that six polymorphisms ATG2B rs3759601, ATG16L1 rs2241880, ATG10 rs1864183, NOD2 rs2066844 and rs2066845 and ATG5 rs2245214 were associated with a predisposition to tumor development, particularly in glioblastoma." (PMID 35884904, 2022). "For example, in a mouse CT26 colon tumor model, mitoxantrone and oxaliplatin activate autophagy and enhance tumor-infiltrating dendritic cells and T cells, and depletion of autophagy-associated proteins (ATG5 or ATG7) reduces chemotherapy-induced anti-tumor immune responses." (PMID 35740594, 2022). "Besides that, specific deletion of two essential genes, ATG7 or ATG5, in Treg cells impaired their survival fitness and lineage stability, leading to loss of Treg and greater tumor resistance." (PMID 35600411, 2022). "Neoplasia has been found in the liver and pancreas of various autophagy-deficient mouse models, including Becn1 heterozygous mice, systemic mosaic Atg5 deletion mice, and liver- or pancreas-specific Atg5 or Atg7 deletion mice." (PMID 35646940, 2022). "Likewise, deficiency of core autophagy genes like Atg7, Atg5, and Fip200 represented tumor suppression effects." (PMID 34365465, 2021). "As the Atg-5 and Atg-7 genes are related to autophagosome formation, the deletion of the Atg-5 gene in mice can cause the development of multiple benign tumors in the liver, and the liver-specific deletion of Atg-7 in mice also induces tumor production." (PMID 35155196, 2021). "Aspirin also improved tumor control by immunogenic chemotherapeutics, and this effect was lost in T cell-deficient mice, as well as upon knockdown of an essential autophagy gene (Atg5) in cancer cells." (PMID 33298861, 2020). "In addition, the use of shRNA against the ATG5 and ASICs genes was associated with an extended survival time and a reduction in tumor size in murine heterotopic xenograft model." (PMID 31434275, 2019). "To determine if somatic mutations identified in human tumor samples directly affected this critical interaction between ATG5 and ATG16L1, we next compiled a list of all somatic ATG5 coding-sequence mutations that have been identified across a multitude of human tumors and cancer cell lines." (PMID 31636955, 2019).
tumor (continued). "Furthermore, through regulated degradation of the transcription factor PU.1, autophagy has also been shown to limit Th9 differentiation, and T cells deficient in ATG3 or ATG5 show increased IL-9 production and improved IL-9-mediated tumor control." (PMID 31632966, 2019). "To characterize the role of myeloid cell autophagic pathways in tumor progression, we generated a myeloid cell-specific targeted deletion of the autophagic gene Atg5 by crossing mice carrying the lox-P flanked Atg5 allele to mice carrying lysozyme M (LysM) promoter-driven Cre recombinase." (PMID 28686632, 2017). "Also other autophagy-involved proteins, such as UV radiation resistance-associated gene (UVRAG), Atg5, and Atg7, were recently described as tumor suppressors." (PMID 28725634, 2017). "Similar to CR, autophagy deficiency (Atg5−/−) decreased tumor growth in control-fed mice." (PMID 27651895, 2016). "Tumor incidence of 1 × 107 Atg5-deficient CD271+ cells was reduced to one-fifths." (PMID 27863492, 2016). "Finally, we clarified whether Atg5 overexpression in autophagy‐deficient MEF cells (clone A) affects tumor formation in vivo." (PMID 38826147, 2024). "For instance, in cells with defective apoptosis mechanisms, autophagy often serves as an alternative cell death pathway; however, in cells where key autophagy genes are mutated or deleted, such as BECN1 or ATG5, autophagy may fail to execute its tumor-suppressive role effectively." (PMID 39315094, 2024). "Interestingly, the authors also noted that the initial transition from hyperplasia to adenoma in autophagy‐deficient mice was higher, suggesting that the loss of Atg5 in this model promotes the early stages of tumor development, whilst blocking the later stages." (PMID 35689420, 2022). "Administration of nimbolide after 8 weeks of DMBA painting arrested tumor growth associated with induction of apoptosis and inhibition of autophagy as evidenced by a significant increase in Bax and cleaved caspase-9 and -3 with downregulation of Bcl-2, Beclin, ATG5, and LC-3." (PMID 30352996, 2018). "Besides Beclin1, other autophagy-related proteins such as Atg4c, Atg5, and Atg7 also were found to have tumor suppressor functions in mice models and mutations autophagy-related genes such as ATG2B, ATG5, ATG9B, ATG 12, and UVRAG have been described in gastrointestinal cancers as well." (PMID 25741318, 2015). "Pharmacological blockade and autophagy-rescue experiments (using si-ATG5 and chloroquine) indicate that this mitophagy-dependent quality control promotes tumor migration and buffers reactive oxygen species (ROS) to sustain OXPHOS capacity." (PMID 42212314, 2026). "Under tumor-mimicking immunosuppressive conditions, ATG5 OE CAR-T cells maintained cytotoxic activity during prolonged antigen exposure and exhibited preserved effector cytokine production together with reduced oxidative stress." (PMID 42099602, 2026). "The study demonstrated that the electrostatic interaction drives the CQ + DTX + Atg5 siRNA NPs, further resulting in the encapsulation of CQ and Atg5 siRNA in NPs, which can augment the responsiveness of tumor cells to DTX." (PMID 41304956, 2025). "Deletion of Atg5 or Atg7 in KRasG12D-driven spontaneous lung cancer models reduced tumor size compared with that in wild type (WT) mice." (PMID 41408407, 2025). "Elevated ATG5 expression correlates with higher tumor grade, increased tumor size, advanced clinical stage, and lymph node metastasis in OSCC." (PMID 40951345, 2025). "Accumulating evidence demonstrated that ATG5 has a significant impact on autophagy that leads to chemoresistance in various tumor cells." (PMID 41282485, 2025). "However, induction of deficient autophagy through deletion of Atg5 or Atg7 in mice leads to benign liver tumors, indicating that autophagy could play an essential role in inhibiting tumor initiation in liver, which necessitates further research in human cancers." (PMID 40248706, 2025).
tumor (continued). "m6A-modified USP13 induces autophagy and imatinib resistance in gastrointestinal stromal tumor cells by regulating ATG5 stability." (PMID 40781108, 2025). "It is possible that ATG5 degradation was more prevalent in patients with superior tumor biology, leading to its detection in serum and observed improved outcome." (PMID 41294712, 2025). "Although the importance of autophagy in PDAC has been demonstrated by the tumor-suppressive effects of Atg5 and Atg7 deletion, the role of ULK1, a key initiator of autophagy, remains underexplored in in this context." (PMID 41408407, 2025). "Combination therapy with ENZ and CQ enhances the therapeutic efficiency by decreasing tumor growth and inducing apoptosis, which is achieved by genetic suppression of autophagy using Atg5 siRNA." (PMID 40248706, 2025). "Its evidence is present when autophagy-associated proteins like ATG5, ATG7, and Beclin-1 are impaired, and then spontaneous tumors are reported, suggesting their tumor suppressive function." (PMID 40444035, 2025). "Previous research has demonstrated that the upregulation of ATG5 expression following treatment with chemotherapeutic agents activates the autophagy pathway, leading to the inhibition of tumor cell proliferation and the promotion of apoptosis." (PMID 39629073, 2024). "GZ17-6.02 interacted with bortezomib to enhance autophagosome formation and autophagic flux, and knock down of ATM, AMPKα, ULK1, Beclin1 or ATG5 significantly reduced both autophagy and tumor cell killing." (PMID 38441437, 2024). "The autophagy findings were closely reflected in our data examining tumor cell killing, where the dose-dependent killing effect was profoundly reduced with knock down of Beclin1 or ATG5 but remained present in cells that had ATM or AMPKα knocked down." (PMID 38329728, 2024). "Research has demonstrated that suppression of autophagy-related genes, such as Beclin-1 and ATG5, diminishes the migratory and invasive potential of tumor cells, attributed to reduced availability of energy and materials essential for these processes." (PMID 39655055, 2024). "Autophagy plays an important role in both tumor suppression and tumor promotion, and mice with systemic mosaic deletion of Atg5 and liver-specific Atg7−/− can develop benign liver adenomas." (PMID 38338839, 2024). "At different stages of polyoma middle T (PyMT) mammary tumor progression in mice, knockout of ATG5 or ATG12 profoundly inhibited primary tumor growth." (PMID 38482052, 2024). "Accordingly, rescuing the autophagy deficiency of clone A by overexpression of Atg7 gene shifts the role of Atg5 from pro‐tumor to anti‐tumor status, indicating the dual role of Atg5 in tumorigenesis." (PMID 38826147, 2024). "Knock down of CD95 interacted in an additive fashion with knock down of Beclin1 or ATG5 to further reduce tumor cell death below that observed for any of the individual knock downs." (PMID 38329728, 2024). "Consistent with our in vitro data, the main proteins involved in autophagosome formation, namely ATG12-ATG5 (ATG5) and Beclin 1, were upregulated in tumor tissue following single treatment with Abi." (PMID 39409882, 2024). "Through the circTGFBR2/miR-205-5p/ATG5 axis, researchers indicated that circTGFBR2 is an innovative tumor promoter circRNA in hepatocytic exosomes that accelerates HCC growth by amplifying ATG5-mediated protective autophagy." (PMID 39315094, 2024). "For example, the immunosuppressive effect of Tregs is highly autophagy dependent, and ATG5 or ATG7 deletion in T cells induces severe tumor implantation rejection in isogenic mouse tumor models." (PMID 38918278, 2024). "Herein, we observed that clone A of Atg5‐overexpressed Atg7−/− MEF cells induced larger tumor size compared to positive control M5R cells at day 3 p.i., followed by rapid regression." (PMID 38826147, 2024).